VHL (von Hippel-Lindau tumor suppressor)
Diseases named in the same sentence as VHL in open-access papers (continued):
Sharing a sentence is not in itself a finding about the gene and the disease.
cancer (continued). "Malignant tumours are rare (< 5%) in RET, VHL, SDHD, SDHC, SDHAF2 and TMEM127 mutations." (PMID 29166454, 2017). "Moreover, because Daam2-VHL expression demonstrates a robust, inverse correlation across a spectrum of cancers, this is likely to be a generalized mechanism of VHL suppression in cancer." (PMID 29053101, 2017). "Given that Daam2 expression is inversely correlated with VHL, we next assessed whether Daam2 demonstrates congruent correlation with HIF1α and pAkt in the panel of human cancers." (PMID 29053101, 2017). "In addition, future studies should be integrated with genomics data to assess the effects of mutations of genes commonly mutated in ccRCC (e.g. VHL, SETD2, BAP1) on the cancer kinome." (PMID 28418903, 2017). "Alterations in iron uptake may play a unique role in RCC, since this cancer is often defined by a dysregulated VHL/HIF-α pathway that governs intracellular iron levels." (PMID 29291011, 2017). "This study was of interest because many VHL mutations involved in human cancer, especially those found in PGLs, are not always accompanied by loss of the wild type allele." (PMID 28036268, 2017). "In contrast, the inhibition of miR-28-5p in checkpoint-deficient VHL-negative cancer cells restored Mad2 levels." (PMID 29165391, 2017). "Thus, our findings provide deeper understanding of the roles of VHL isoforms and their distinct oligomeric states in cancer." (PMID 28580172, 2017). "Protein screening and bioinformatics studies revealed that Daam2 and VHL expression is inversely correlated across a broad spectrum of cancers, while functional interrogation of this relationship demonstrated that Daam2 promotes tumorigenesis via suppression of VHL expression." (PMID 29053101, 2017). "Furthermore, 72 cases of ccRCC patients with cancer and corresponding adjacent tissues in database GEO were used to verify the relationship among VHL, HNF-4α and ALDH2." (PMID 28643803, 2017). "Although inheritance of VHL mutations causes a predisposition for ccRCC, deletion of VHL is not sufficient to cause cancer, and the loss of VHL alone provides neither prognostic nor therapeutic prediction values." (PMID 27100670, 2016). "In cancer, the key methylation event contributing to tumorigenesis is considered to be promoter hypermethylation, which results in the inactivation of a wide range of tumor suppressor genes such as VHL, p16 and MLH116." (PMID 27677595, 2016). "Reviews of registry data indicate that patients with VHL-associated RCC have a higher primary tumor size threshold for metastatic disease, a significantly higher overall survival, and an increased cancer-specific survival when compared to patients with similarly sized sporadic RCC." (PMID 27047799, 2016). "The Cancer Genome Atlas Research Network supports the fundamental role of oxygen-sensing genes (VHL) and chromatin remodeling genes (PBRM1, BAP1 and SETD2) in RCC tumorigenesis, highlighting their potential as prognostic biomarkers and/or future therapeutic targets." (PMID 26452128, 2015). "Therefore, the selectivity of TGX221 for both VHL and SETD2 implies an inherent connection between those common mutations in a variety of cancers." (PMID 25853938, 2015). "As cited by Alpeers2, some individuals with inherited germiline VHL mutations never develop cancer as second mutation never occurs." (PMID 25097537, 2014). "Thus, in VHL-knockdown WT1-expressing cancer cells, markers of both EMT and MET coexisted, and these cells displayed epithelial-like morphology." (PMID 25025131, 2014).
cancer (continued). "Epigenetic lesions in DNA without mutations in the coding regions have been shown to be common phenomena in the pathogenesis of a wide range of cancers, especially the methylation-mediated silencing of tumor suppressor genes such as VHL, p16INK4a, E-cadherin, hMLH1, BRCA1, and LKB1." (PMID 24829571, 2014). "In contrast, 25% of the deletions resulting in VHL cancer are greater than 10,000 bp." (PMID 23755193, 2013). "It will be interesting to test in the future whether oxygen/PDH/VHL-independent HIFα degradation is in general the key regulator of the HIF activity differences observed in cancer cell lines under the same level of hypoxia." (PMID 22132102, 2011). "The discrepancy between VHL studies in CCRCC could also be explained by the stage of cancer progression at which VHL status was evaluated." (PMID 19755989, 2009). "Our prior investigation in eupoloid primary ES cell lines, utilized as a strategy to avoid interference from transforming cancer cell events, demonstrated a bias toward HIF-2α dysregulation for VHL Type 2B mutation, and a graduated degree of HIF dysregulation across the disease subtypes." (PMID 19030229, 2008). "The hypoxic microenvironment resulting from the rapid oxygen consumption of rapidly dividing cancer cells causes the accumulation of hypoxia-inducible factor-1α (HIF-1α) due to reduced catalytic activity of prolyl hydroxylase domain 2 (PHD2) and Von Hippel-Lindau (VHL)." (PMID 41614951, 2026). "Furthermore, VHL and tumors are closely related to clinical outcomes and their genetic information may predict patient responses before cancer treatment." (PMID 40005423, 2025). "Interrupting the Pin1/CDK1/pVHL axis results in decreased cancer cell proliferation, migration, invasion, and chemoresistance, and therefore it could be therapeutically valuable in treating cancers with wild-type VHL." (PMID 38727267, 2024). "However, given the VHL/HIF–mediated axis leading to a robust upregulation in cancer cell aerobic glycolysis, it is possible that VHL-deleted ccRCC cancer cells are an exception to this finding so that glucose competition may occur in the TME." (PMID 38618956, 2024). "In addition, mutations in VHL genes, which are the most frequently mutated in ccRCC, did not affect PD-L1 mRNA levels in cancer tissues." (PMID 39375538, 2024). "HIF1α may promote miR-183/96/182 cluster expression in an HBXIP-dependent manner, out of which miR-183 can target VHL mRNAs and inhibit its expression, thereby constitutively promoting HIF1α-driven tumorigenesis and cancer progression in a feedback loop mechanism." (PMID 37583933, 2023). "Previous studies have reported that HIF inhibits mTOR activity through the transcriptional induction of antagonists of mTOR signaling, raising a question as to whether the use of mTOR inhibitors constitutes a rational approach to the treatment of VHL-defective cancer." (PMID 36097292, 2022). "However, the VHL status alone cannot predict the differential sensitivity of ccRCC to cancer treatments, which suggests that other molecular differences may contribute to the differential response of ccRCC cells to drug therapies." (PMID 30909494, 2019). "Thus, VHL functions as a methylated gene in different cancers." (PMID 29933410, 2018). "Therefore, it is promising that VHL can be used as a tool to degrade the “undruggable” targets in cancer that may achieve efficient therapeutic effects in cancer therapy." (PMID 29562667, 2018). "Since loss of VHL is found in the majority of sporadic RCC and JunB is up-regulated in the VHL-deficient RCC specimens, these results suggest that CCL2 production by cancer cells via aberrant JunB expression might be a predominant mechanism to enhance TAM accumulation in RCC." (PMID 30483271, 2018).
cancer (continued). "Given that most tumors carrying VHL inactivating mutations are not necessarily accompanied by loss of heterozygosity, we also analyzed the impact of a VHL cancer-associated mutation, F76del VHL, on miR-210 expression by using SCC40 cells which, endogenously, express wild type VHL." (PMID 28036268, 2017). "Our results further show that VHL may be a driver of MXRA5 expression in cancer cells." (PMID 27599751, 2017). "Previously, an analysis of several London OTA/rat carcinomas did not identify evidence of mutations in the rat orthologues of human familial renal cell carcinoma genes VHL and FLCN (Ricketts and Maher, personal communication), and genome-wide genetic sequencing studies are currently in progress." (PMID 29182526, 2017). "This makes it difficult to conclude whether NDR-acquiring CGI promoters are more likely to be the result of a cis versus trans mechanism, but this question is central to understanding how CGI promoters for cancer driver genes like MLH1, BRCA1, and VHL become epigenetically silenced in cancer." (PMID 25747664, 2015). "Finally, we explored whether similar disruptions were present in another VHL-inactivated cancer type, RCC." (PMID 25298778, 2014). "Importantly, findings in VHL-/- cancer cells demonstrated that the shRNA-mediated inhibition of EGFR was sufficient to abolish HIF-2α-induced spheroid formation in a three-dimensional tumorigenic assay, which suggests that EGFR is required for HIF-2α-mediated tumorigenesis." (PMID 24376819, 2013). "The accumulation of HIF-1α has been associated with cancer causing mutations including loss of VHL or PTEN and activation of signalling via RTK, non-RTK and G-protein-coupled receptor through activation of the PI3K and ERK MAPK pathways in a cell type-specific manner." (PMID 21897387, 2011). "Furthermore, hypoxic treatment of various cancer cell lines result in increased PKM2 mRNA, suggesting that this protein may be important in the HIF-1 response, as is most pronounced in VHL-deficient RCCs." (PMID 17123452, 2006). "EGFR activation/signaling and hypoxia, unlike the VHL mutation, are characteristic of many cancers." (PMID 17083723, 2006). "Endogenous VHL is also utilized by proteolysis-targeting chimera (PROTAC) protein degraders, a promising class of anti-cancer agents." (PMID 41420106, 2025). "All five patients with multiple PCCs completed genetic testing, and 3 (60.0%) tested positive for an LPV/PV in a hereditary cancer gene, all of which were hereditary PGL/PCC genes (RET = 2, VHL = 1)." (PMID 39539798, 2024). "Hypermethylation of cancer suppressor genes such as RB1, CDKN2A, MLH1, VHL, and BRCA1, leading to their repression, has been observed in various cancer types." (PMID 38970307, 2024). "Meanwhile, we found E2F3 (transcription factor 3), which correlated with poor prognosis in a variety of cancers, was negatively regulated HOOK1 transcription though directly binding to the HOOK1 promoter by VHL dependent manner in RCC." (PMID 37085921, 2023). "The hypoxia signaling pathway is now a novel target of cancer research, being assessed in multiple clinical trials, and with Belzutifan, a HIF2α inhibitor being recently FDA-approved for VHL-driven cancers." (PMID 37371779, 2023). "Homo-PROTACs have recently been reported to target MDM2104, VHL, and CRBN, revealing new chemical probes to achieve the selective degradation of E3 ligases and offering promising cancer intervention techniques." (PMID 37667522, 2023). "In conclusion, the results showed that VHL and cIAP-based degraders were an attractive approach for targeted degradation of CDK4/6 in cancer." (PMID 35680848, 2022).
cancer (continued). "We plotted ccRCC cell lines available in the Cancer Cell Line Encyclopedia (CCLE) as well as 786-O-Ctrl and 786-O-VHL on the two-dimensional space using the linear discriminant analysis (LDA) of their transcriptome and labeled their VHL status." (PMID 35159281, 2022). "Among newly identified genes, eleven other cancer targets were detected: MPL; ERBB4; VHL; FGFR3; KIT; KDR; PTEN; KRAS; PTPN11; ERBB2; and SMARCB1." (PMID 35621644, 2022). "HIF-1 also increases oncogene activity through the inactivation of tumor suppressors (e.g., VHL) and through PI3K/AKT/mTOR in cancer cells, ultimately driving cancer progression and metabolic alterations that are resistant to treatment." (PMID 36778600, 2022). "To gain a pan-cancer perspective on alterations to these genes, we evaluated the DNA CN status of VHL, CUL2, RBX1, ELOC, and ELOB across 33 cancer types processed by TCGA." (PMID 35664333, 2022). "Since VHL was poorly expressed in platelets, degrader 74 (DT2216) was more potent against various Bcl-xl-dependent leukemia and cancer cells but considerably less toxic to platelets than ABT-263 in vitro." (PMID 35680848, 2022). "We have listed several representative PROTACs based on CRBN, VHL, MDM2, or cIAP1 E3 ligases, and PROTACs that are undergoing anti-cancer clinical trials." (PMID 36557960, 2022). "For instance, lincRNA-p21 binds von Hippel-Lindau (VHL) protein and HIF-1α separately, disrupting their interaction and stabilizing HIF-1α to enhance glycolysis in cancer cells." (PMID 35659362, 2022). "Because platelets express a low level of VHL E3 ligase, DT2216 has minimal effect on platelets but exhibits an improved cytotoxicity against various cancer cells that are dependent on BCL-XL for survival." (PMID 33627663, 2021). "More than 600 E3 ligases have been found in the human genome; however, only a few E3 ligases have been used in PROTAC designs for various cancer targets, including CRBN, VHL, IAP, MDM2, and β-TrCP." (PMID 34943817, 2021). "In ccRCC, the PI3K–Akt signaling pathway is constitutively activated and shows critical role in cancer progression through regulating various targets, such as bromodomain-containing protein 4 (BRD4) and VHL–HIF pathway." (PMID 34244473, 2021). "For example, VHL-based PROTAC for BCL-xl is more tolerable than BCL-xl inhibitor ATB263, in part due to the relatively low expression of VHL in platelets than in cancer cells, thus reducing potential on-target toxicity." (PMID 34350175, 2021). "Respectively, VHL and HIF1 are the direct and indirect targets of miR-224, which is upregulated in RCC and displays an oncogenic role in many cancer types." (PMID 33918154, 2021). "Several studies reported HIF1 and VHL to be direct targets of miR-17-5p, which appear dysregulated in RCC and induces proliferation and migration in various cancer types." (PMID 33918154, 2021). "However, the Chi-squared test χ2 revealed, after exclusion of gender-specific cancer diseases, five different genetic mutations that are significantly more common in men than in women: CDKN2A (p = 0.04), CTNNB1 (p = 0.002), KIT (p = 0.0005), SLX4 (p = 0.034), and VHL (p = 0.046)." (PMID 33114048, 2020). "We generated, for the first time, highly active VHL-based PROTACs with considerable CDK6 selectivity in a broad range of different human and murine cancer cells." (PMID 33133483, 2020). "Another miRNA, miR-23a/b is delivered from adipocytes to cancer cells, and miR-23a/b was shown to act to modulate HCC cells by repressing the expression of VHL/HIF-1α." (PMID 33297338, 2020). "In conclusion, we show that VHL- and IAP-based PROTACs are an attractive approach for targeted degradation of CDK4/6 in cancer." (PMID 33133483, 2020). "In ccRCC, the alterations of VHL mostly disrupt the function of pVHL so that HIF‐1/2ɑ cannot be degraded and are accumulated in the cancer cell even under normoxic conditions." (PMID 32537867, 2020).
cancer (continued). "The variability in VHL-PROTAC design has enabled these molecules to degrade a vast number of disease-related proteins, particularly those involved in cancer." (PMID 31500395, 2019). "Akt and mTORC1 pathway activation is common in many human cancers, including ccRCC and is mediated by phosphoinositide kinase 1 (PDK-1), the VHL/EGLN suppressive pathway, and the mTORC2 complex." (PMID 31519159, 2019). "Other studies in cancer cells have shown that HIF-1α-induced lincRNA-p21 bind HIF-1α and VHL and thus disrupt the VHL–HIF-1α interaction and promote HIF-1α accumulation." (PMID 29383635, 2018). "Hypermethylation of the CpG islands was one of the major factors underlying the inactivation of tumor suppressor genes such as Rb, VHL, hMLH1, and BRCA1 in cancer." (PMID 29462183, 2018). "Furthermore, VHL target genes (direct or indirect) that suppress oxidative stress were elevated during the blebbishield emergency program, indicating that management of oxidative stress during the blebbishield emergency program helps cancer stem cells to override apoptosis." (PMID 28580172, 2017). "Pathways in Cancer describe of 251/327 genes RAF1 and VHL again as G1 nominators followed by WNT7A (15/26) and MLH1 (22/26) with p<0.00553, respectively p<0.00985." (PMID 28486536, 2017). "Among the differentially expressed genes in primary samples, 7 of 39 genes (VHL, GNE, POLH, MAPK13, NOP14, INADL, CDC5L) were reported to be cancer-related in the literature." (PMID 28009993, 2017). "As for this, 114 cases of RCC samples were collected to detect the expression of VHL, HNF-4α and ALDH2 in cancer and adjacent tissues by immunohistochemical assay." (PMID 28643803, 2017). "Significantly lower expression of VHL, HNF-4α and ALDH2 were found in cancer tissues than their corresponding adjacent tissues." (PMID 28643803, 2017). "By using high-affinity polypeptide monobody binders of human SHP2 and a nanobody recognizing human ASC protein conjugated to the CUL2 substrate receptor VHL, we achieve near-complete proteolysis of endogenous SHP2 and ASC in human cancer cell lines." (PMID 28490657, 2017). "In a pan-cancer analysis, we found that genomic aberrations in BRAF and VHL exhibit downstream effects that are clearly distinct from other genes." (PMID 29322935, 2017). "RNAi silencing of wsb1 in cancer cells under normoxia and hypoxia treatment stabilizes VHL, while inhibition of the WSB1 effect with MG132, a proteasome inhibitor, led to VHL survival." (PMID 27542736, 2016). "Lastly, with the von Hippel–Lindau tumor suppressor (pVHL) and the hypoxia inducible factor-1α (HIF-1α)—playing an important role in cancer malignancy and metastasis." (PMID 24272675, 2014). "pVHL targets HIFα for degradation, so HIFα protein stabilizes and becomes constitutively active in VHL-defective ccRCC cancer cells." (PMID 24260413, 2013). "However, it was recently suggested a new cause of occupational cancer where there was a molecular analysis of VHL without mutation detected in this gene, suggesting that other genes may be implicated in RCC and in particular linked to chemical exposure." (PMID 17997830, 2007). "We find that, in additional to inhibiting hypoxia-inducible factor 2α (HIF2α), a major oncogenic driver in Von Hippel-Lindau (VHL)−/− ccRCC, YAP also blocks nuclear factor κB (NF-κB ) signaling in ccRCC to inhibit cancer cell growth under conditions where HIF2α is dispensable." (PMID 38979373, 2025).